GAGE13 (G antigen 13)
Synonyms: GAGE-13; GAGE-12A; GAGE12A; OTTHUMG00000024138
Tractability: Antibody: the Human Protein Atlas places it where antibodies can reach.
Gene: Protein-coding gene on chromosome X (49,331,582 to 49,338,949, forward strand). Ensembl gene ENSG00000274274.
Subcellular location (Human Protein Atlas): Plasma membrane; Cytosol; Golgi apparatus
Homologues: Orthologues: chimpanzee GAGE10 (84% identical). Paralogues in human: GAGE1 (98% identical), GAGE12F (98% identical), GAGE12G (98% identical), GAGE12J (98% identical), GAGE12C (97% identical), GAGE12D (97% identical), GAGE12E (97% identical), GAGE12H (97% identical), GAGE2A (97% identical), GAGE10 (92% identical), GAGE2E (92% identical), PAGE1 (54% identical), and 10 more.
Diseases named in the same sentence as GAGE13 in open-access papers:
GAGE13 is named in the same sentence as 2 diseases in open-access papers, as found by Europe PMC text mining. Sharing a sentence is not in itself a finding about the gene and the disease.
GAGE13 shares sentences with these, for which no sentence is quoted: cancer (1 paper); tumor (1).